WRAP73 (WD repeat containing, antisense to TP73)
Description:
The SSX2IP:WRAP73 complex is proposed to act as regulator of spindle anchoring at the mitotic centrosome. Required for the centrosomal localization of SSX2IP and normal mitotic bipolar spindle morphology. Required for the targeting of centriole satellite proteins to centrosomes such as of PCM1, SSX2IP, CEP290 and PIBF1/CEP90. Required for ciliogenesis and involved in the removal of the CEP97:CCP110 complex from the mother centriole. Involved in ciliary vesicle formation at the mother centriole and required for the docking of vesicles to the basal body during ciliogenesis; may promote docking of RAB8A- and ARL13B-containing vesicles.
Synonyms: WDR8
Tractability: PROTAC: ubiquitination databases record sites on it.
Gene: Protein-coding gene on chromosome 1 (3,630,767 to 3,652,761, reverse strand). Ensembl gene ENSG00000116213.
Subcellular location: Cytoplasm; Cytoplasm, cytoskeleton, microtubule organizing center, centrosome; Cytoplasm, cytoskeleton, microtubule organizing center, centrosome, centriole; Cytoplasm, cytoskeleton, microtubule organizing center, centrosome, centriolar satellite
Subcellular location (Human Protein Atlas): Mid piece; Principal piece
Gene Ontology:
Molecular function: protein binding
Biological process: mitotic spindle assembly; positive regulation of non-motile cilium assembly; microtubule anchoring at mitotic spindle pole body
Cellular component: centrosome; ciliary basal body; microtubule organizing center; MWP complex; centriolar satellite; centriole; cytoplasm
Genetic constraint (gnomAD): Loss-of-function variants: 52 observed, 59.32 expected, observed/expected ratio (o/e) 0.88, 90% interval 0.7 to 1.1. The upper end of that interval is the gene's LOEUF score, 1.1, which puts it in group 4 of 6, group 1 being the genes least tolerant of losing a copy. Missense variants: 548 observed, 581.63 expected, observed/expected ratio (o/e) 0.94, 90% interval 0.88 to 1.01. Synonymous variants: 237 observed, 244.94 expected, observed/expected ratio (o/e) 0.97, 90% interval 0.87 to 1.08.
Homologues: Orthologues: chimpanzee WRAP73 (99% identical), dog WRAP73 (90% identical), guinea pig WRAP73 (88% identical), mouse Wrap73 (88% identical), rat Wrap73 (87% identical), pig WRAP73 (85% identical), macaque WRAP73 (83% identical), zebrafish wrap73 (70% identical), tropical clawed frog wrap73 (69% identical).
Diseases named in the same sentence as WRAP73 in open-access papers:
WRAP73 is named in the same sentence as 3 diseases in open-access papers, as found by Europe PMC text mining. Sharing a sentence is not in itself a finding about the gene and the disease. The quoted sentences say what the papers report.
osteoporosis (1 paper, 2022). A condition of reduced bone mass, with decreased cortical thickness and a decrease in the number and size of the trabeculae of cancellous bone (but normal chemical composition), resulting in increased fracture incidence. "Using ML methods, we identified PLA2G2A and WRAP73 as the optimal combined biomarker set for predicting the risk of osteoporosis, and constructed a related nomogram for practical use." (PMID 35580864, 2022). "We therefore propose that PLA2G2A and WRAP73 may influence the development of osteoporosis by regulating bone remodeling." (PMID 35580864, 2022).
WRAP73 also shares sentences with these, for which no sentence is quoted: Crohn disease (1 paper); unipolar depression (1).